UBA1 (ubiquitin like modifier activating enzyme 1)
Diseases named in the same sentence as UBA1 in open-access papers (continued):
Sharing a sentence is not in itself a finding about the gene and the disease.
cancer (continued). "When samples from all tumor types were included, there was a slight, but significant, positive correlation between UBA1 and NEDD8 expression (R = 0.134), which would suggest that in many cancers as NEDD8 levels increase there is also an increase in UBA1." (PMID 34685640, 2021). "The silencing of UBA1 has been shown to repress the proliferation, migration, invasion, and increase ferrous iron and MDA levels in live cancer cells." (PMID 33344241, 2020). "The opposite relationship between UBA1 and UBA6 in immune infiltration may account for the different prognosis of cancer patients." (PMID 40046044, 2025). "In conclusion, UBA1 and UBA6 are critically involved in various diseases and cancers." (PMID 40046044, 2025). "In line with the notion that UBA1 is an essential gene in cancer cells, we achieved partial depletion but not complete knockout of Uba1 in these models." (PMID 39540840, 2025). "This raises the possibility that under excessive inflammation, common in many cancers, hematopoietic cells may utilize the UBA6/FAT10 axis instead of the UBA1/Ub axis." (PMID 40588566, 2025). "In a comparison of the control with cancer group (grade 4), the 5-marker panel (CCT3, PCMT1, TKT, TOMM34, UBA1) showed better sensitivity (0.90 and 0.90), specificity (0.93 and 1.00), error rate (8 and 4%), and AUC value (0.94 and 0.96) than the best single marker (TOMM34)." (PMID 37875819, 2023). "This has been demonstrated by gene ablation studies in yeast and C. elegans where UBA1 is the only ubiquitin E1, but also in various human cancer cell lines where UBA6 is apparently not able to compensate for the loss of UBA1." (PMID 33732684, 2020). "The expression level of UBA1 may be influenced by clinical parameters and the number of clinical information datasets available for cancer patients in this study is limited, therefore, the expression level of UBA1 in some cancer patients may not be accurate." (PMID 39183260, 2024). "Notably, other E1 inhibitors like TAK-243, TAS-4464 and ML-792 targeting ubiquitin-like modifier-activating enzyme 1 (UBA1), NAE and SUMO E1 activating enzyme, respectively, have been investigated in several cancer models, both in vitro and in vivo, and encouraging results have been reported." (PMID 36140335, 2022). "However, in certain cancer types, there were statistically significant negative correlations between UBA1 and NEDD8 expression, including colon and rectal cancers (R = −0.1414) and lung adenocarcinoma (R = −0.1983)." (PMID 34685640, 2021).
tumor (31 papers, 2008 to 2026). "Conversely, increased nuclear UBA1 expression in tumor cells was associated with worse outcomes in the luminal B subtype." (PMID 42038032, 2026). "Among the eight E1 enzymes members identified, UBA1 has been shown to be most important where loss-of-function exerts the most unfavorable effect on the survival and growth of tumor cells." (PMID 33805973, 2021). "That Uba1 was exclusively mutated in tumors that developed in the absence of an adaptive immune response suggests it is only an effective tumor driver in an immunocompromised microenvironment." (PMID 31338332, 2019). "A vital ancestral role for Uba1 is supported by its highly conserved counterpart in Drosophila, which is implicated as a tumour-suppressor gene." (PMID 31772231, 2019). "Furthermore, UBA1 expression was analysed separately in both tumor cells and tumor-associated stroma." (PMID 42038032, 2026). "Importantly, restoration of UBA1 reversed the tumor growth impairment caused by Uba1 depletion, confirming that the CRISPR-mediated depletion of Uba1 was on-target." (PMID 39540840, 2025). "Cells adjacent to clones for strong alleles of Uba1 overproliferate because of increased Notch signaling, suggesting that Uba1, through its role in ubiquitination, may act as a tumor suppressor gene." (PMID 36824528, 2022). "It is feasible that mutation of Uba1, a ubiquitinase also known to be involved in protein folding and degradation, leads to the generation of innumerable antigenic peptides that facilitate clearance of the tumor cells in the presence of functional lymphocytes." (PMID 31338332, 2019). "Multivariable Cox regression analyses revealed that UBA1 expression in tumor cells was an independent prognostic marker." (PMID 42038032, 2026). "Collectively, these data indicate that UBA1 plays a role in evading T-cell–mediated immune surveillance, thereby promoting tumor growth." (PMID 39540840, 2025). "Surface MHC-I without antigen loaded is unstable at physiological temperatures; therefore, these data suggest that UBA1 inhibition increases antigen presentation and results in tumor recognition by CD8+ T cells." (PMID 39540840, 2025). "This study investigated the association between the expression levels of UBA1 and UBA6 in diverse tumor types and their implications for diagnosis and prognosis." (PMID 40046044, 2025). "We observed that simultaneous depletion of both CD4+ and CD8+ T cells resulted in a much stronger rescue of tumor growth in Uba1-depleted tumors." (PMID 39540840, 2025). "We observed significantly reduced levels of JAK1 and MHC-I in tumors with high tumor-specific UBA1 expression compared with UBA1-low tumors." (PMID 39540840, 2025). "We further subjected UBA1-high and UBA1-low human tumor samples to multiplex immunofluorescence staining." (PMID 39540840, 2025). "Through the use of syngeneic murine cell lines with partial Uba1 depletion and models of Uba1 overexpression, we established that UBA1 facilitates tumor progression and diminishes intratumoral CD8+ T cell levels." (PMID 39540840, 2025). "This trend was further validated in paired tumor samples exclusively from the TCGA database, underscoring UBA1 as a gene with elevated expression in tumor samples." (PMID 39684409, 2024). "In this study, the correlation between UBA1 mRNA levels and tumor-infiltrating immune cells was assessed in individuals with BC by means of ssGSEA." (PMID 39684409, 2024). "This study elucidates the oncogenic function of UBA1 in BC and suggests a potential link between UBA1 and tumor–immune interactions." (PMID 39684409, 2024). "It was observed that both UBA1 mRNA and protein expression were significantly heightened in BC tumor tissues in comparison with adjacent normal tissues in the TCGA database and The Human Protein Atlas." (PMID 39684409, 2024). "UBA1 is considered an attractive potential anti-tumor therapeutic target and a key regulator of DNA double-strand break repair and genome replication in human cells." (PMID 36959858, 2023).
tumor (continued). "Collectively, these results imply that AZGP1P2 mediates the stemness and apoptosis of PCSCs and promotes docetaxel therapeutic effect by suppressing tumor growth and metastasis via UBA1/RBM15-mediated TPM1 mRNA decay in CRPC." (PMID 37854295, 2023). "Expression of EFP, HERC5 and UBA1 in non-tumour tissues were positively correlated with direct bilirubin levels (Spearman's rho =0.31, 0.33 and 0.45; P=0.06, 0.05 and 0.01, respectively)." (PMID 32132870, 2020). "Importantly, in Uba1-overexpressing tumors, we detected diminished surface expression of tumor-specific MHC-I and reduction of mRNA levels of Cxcl10, Cxcl9, and MHC-I genes compared with the control." (PMID 39540840, 2025). "According to functional tests, UBA1 stimulated tumor development by mediating immune escape." (PMID 40098955, 2025). "As expected, tumor cells with high UBA1 expression showed lower JAK1 and MHC-I expression." (PMID 39540840, 2025). "Mechanistically, UBA1 facilitates STUB1-mediated proteasomal degradation of JAK1 in tumor cells." (PMID 39540840, 2025). "Functional studies revealed that UBA1 mediated immune escape to promote tumor growth." (PMID 39540840, 2025). "We found that depletion of Uba1 significantly decreased tumor growth in both syngeneic models." (PMID 39540840, 2025). "We next examined the tumor-specific expression of UBA1, JAK1, and MHC-I in clinical samples." (PMID 39540840, 2025). "In addition to USP22, the ubiquitin-like modifier activating enzyme 1 (UBA1) has been shown to downregulate MHC-I expression for tumor immune evasion." (PMID 41252204, 2025). "Compared with patients without mutations, tumour patients with UBA1 gene mutations have significantly poorer prognosis in OS." (PMID 39183260, 2024). "The drug sensitivity of UBA1 expression in tumours was studied using GSCALite." (PMID 39183260, 2024). "In addition, the specific mechanism by which UBA1 regulates tumor immunity in BC must be explored in further in vitro and in vivo studies." (PMID 39684409, 2024). "To interpret the clinical implication of UBA1 in HCC, we showed that high UAB1 expression was strongly associated with poor survival in HCC patients, and its differential expression was related to tumor grade." (PMID 33344241, 2020). "Additionally, the differential expression of UBA1 was strikingly correlated with tumor grade (p=0.048)." (PMID 33344241, 2020). "While our study supports a pre-eminent role of UBA1 in determining the sensitivity of cSCC cells to MLN7243 under some circumstances suppression of UBA6 could contribute to the anti-tumour activity of this inhibitor." (PMID 29755650, 2018). "One mechanism employed by cancerous cells could be down-regulation of UBA1 expression to stimulate tumor angiogenesis." (PMID 28798148, 2017). "According to our analysis of a rather small number of normal and tumour tissue samples the asbestos-related deregulation of ubiquitination seems neither to be caused by UBA1 nor UBA7." (PMID 19014429, 2008). "In addition, the results of tumor microenvironment-related scores showed that most UBA1/6 expression was significantly negatively correlated with stromal score, immune score and estimation score, and positively correlated with tumor purity, which was particularly significant in ACC." (PMID 40046044, 2025). "However, further research is needed on how UBA1/6 affects tumor progression and stage." (PMID 40046044, 2025). "Therefore, controlling the expression of UBA1/UBA6 in tumors might regulate tumor TME and promote the killing effect of immune cells on tumors." (PMID 40046044, 2025). "Therefore, the abnormal expression of UBA1 may also regulate the stability and function of certain cytokines to regulate the immune escape process of tumour cells, which will be the molecular mechanism to be explored in our further research." (PMID 39183260, 2024). "UBA1 protein levels may thus provide a marker for tumour sensitivity to MLN7243." (PMID 29755650, 2018).
tumor (continued). "More importantly, we urgently need high-throughput sequencing and biological experiments focused on UBA1- and UBA6-specific tumors to address tumor heterogeneity effectively." (PMID 40046044, 2025). "Researches have shown that the expression of UBA1 and UBA6 was closely related to tumor occurrence and progression." (PMID 40046044, 2025). "Therefore, UBA1 might help tumor immune escape by suppressing Tem." (PMID 38481990, 2024). "Through large-scale CRISPRi screening, we discovered genetic modifiers in GBM cells, including ARPC4, PI4KA, ATP6V1A, UBA1, and NDUFV1, that regulated the efficacy of CAR T cell-mediated tumor killing." (PMID 38561797, 2024). "Therapeutic inhibition of E1 enzymes, UBA1 and NAE, induces tumor cell death through unfolded protein response (UPR) and proteotoxic stress in hematologic malignancies." (PMID 33805973, 2021). "In non-tumour tissues, EFP expression was strongly correlated with that of HERC5, UBA1 and USP18 (Spearman's rho =0.81, 0.89 and 0.75; P<0.0001, respectively)." (PMID 32132870, 2020). "The most prominent of these are candidate tumour suppressors; KDM6A (lysine demethylase 6 A), DDX3X (dead-box RNA helicase 3) and UBA1." (PMID 31772231, 2019). "Uba1 overexpression significantly promoted tumor growth in the immunocompetent mice but not in the immunodeficient mice." (PMID 39540840, 2025). "This supports the notion that UBA1 inhibition enhances antigen presentation and thus tumor recognition by CD8+ T cells, as surface MHC-I without loaded antigen is unstable at physiological temperatures." (PMID 39540840, 2025). "In these particular tumor types, it would appear that increased levels of NEDD8 and/or decreased levels of UBA1 are present and could in fact be representative of the conditions used to isolate NEDDylated proteins in vitro." (PMID 34685640, 2021). "The upregulation of EFP, HERC5, UBA1 and USP18 in HCC tissues and the different patterns of correlation of the genes in HCC tumour and in adjacent non-tumour tissues suggest that these genes may play a role in the pathogenesis of HCC." (PMID 32132870, 2020). "We did not detect exposure-related differences in UBA1 or UBA7 levels in the normal or tumour tissue samples." (PMID 19014429, 2008). "Therefore, higher expression of UBA1 may affect the prognosis of haematological malignancies (DLBCL and AML) by promoting sustained cell proliferation, inhibiting cell apoptosis and ultimately leading to tumour formation." (PMID 39183260, 2024). "Here we show that expression of E3 ligases (HERC5 and EFP/TRIM25), UBA1 and USP18 is significantly upregulated in HCC tumours compared to adjacent non-tumour liver tissues." (PMID 32132870, 2020). "Expression of EFP, HERC5, UBA1, and USP18 was significantly higher in HCC tumour tissues compared to the adjacent non-tumour tissues (P=0.006, 0.012, 0.02 and 0.039, respectively)." (PMID 32132870, 2020). "Relative expression of the five genes EFP, HERC5, UBA1, UBC and USP18, which are related to ISGylation, was quantified and compared between HCC tumour and adjacent non-tumour tissues." (PMID 32132870, 2020). "In the SCC group, however, protein expression of both UBA1 and UBA7 were significantly lower in tumour than in the normal tissue, p = 0.02 and p = 0.01 (two-sided t-test), respectively." (PMID 19014429, 2008). "Namely, the protein levels of UBA1 and UBA7 in the tumour and respective normal tissue of asbestos-exposed and non-exposed patients were analyzed due to their role at the early stages of protein ubiquitination and ubiquitin-like modification processes." (PMID 19014429, 2008).
hematologic disorder (16 papers, 2017 to 2025). A disease involving the hematopoietic system. "In our study, we screened 29,000 individuals for UBA1 variants, referred for a broad range of hematologic diseases, and subjected to 62-gene panel sequencing, identifying 232 patients carrying likely disease-causing mutations." (PMID 41068485, 2025). "Mutations identified in the UBA1 gene and in other genes enhancing onco-hematological disorders among patients enrolled in this study." (PMID 40046741, 2025). "In summary, by applying comprehensive WGTS data analyses we identified several potentially clinically relevant UBA1non-M41 variants that contribute to a more detailed and exhaustive description of the landscape of UBA1 variants in hematologic malignancies." (PMID 36823397, 2023). "VEXAS is an acquired autoinflammatory disease caused by somatic mutations of the UBA1 gene; it is characterized by a severe adult-onset chronic inflammation generally associated to haematological disorders." (PMID 36662445, 2023). "Therefore, testing for UBA1 mutations is recommended for adult patients with systemic inflammation, hematologic disorders, and vacuolation of myeloid and erythroid precursor cells to assist in the early diagnosis of the syndrome and to improve prognosis." (PMID 37501758, 2023). "Remarkably, most VEXAS diagnoses in the recent era result from UBA1 testing of patients already followed up for rheumatologic and haematologic disorders even years prior to the actual suspicion, given the very recent discovery of the disease." (PMID 39347920, 2024). "TAK-243 is a selective, mechanism-based UBA1 inhibitor with a broad preclinical efficacy in solid and hematologic malignancies and has entered phase I clinical trials." (PMID 33476303, 2021). "Other studies have identified UBA1 as a novel target for the treatment of hematological malignancies." (PMID 28798148, 2017). "In our comprehensive study, we sequenced 29,000 patients diagnosed with a variety of hematologic malignancies and identified approximately 80 UBA1 variants that are rare or virtually absent in the healthy population." (PMID 41068485, 2025).
neurodegenerative disease (10 papers, 2011 to 2024). A disorder of the central nervous system characterized by gradual and progressive loss of neural tissue and neurologic function. "Protein aggregates, a known cause of neurodegenerative diseases, indicate neurons’ particular vulnerability to UBA1 dysfunction, potentially exacerbated by impaired direct interactions with proteins crucial for neural development (e.g., SMN1, Gigaxonin)." (PMID 39347709, 2024). "Initial work with Drosophila models has shown that mutations associated with modest impairment of UBA1 function and expression lead to a phenotype reminiscent of neurodegenerative disease." (PMID 26432019, 2015). "Mutations in the UBA1 gene in humans disrupt UBA1 levels and function throughout all cells and tissues of the body but manifest as an early-onset neurodegenerative disease where lower motor neurons are particularly affected (XL-SMA)." (PMID 26432019, 2015). "Missense mutations in the UBA1 gene lead to X-linked spinal muscular atrophy (SMAX2), and reduced UBA1 levels affect UPS-mediated degradation of misfolded proteins leading to neurodegenerative diseases, such as AD." (PMID 32455657, 2020). "Recent work, however, has specifically implicated the main upstream E1 ubiquitin-activating enzyme (UBA1) in a range of neurodegenerative diseases, suggesting a central role for UBA1 in the regulation of neurodegeneration." (PMID 26432019, 2015). "In this review we discuss recent findings that put UBA1 at the centre of cellular homeostasis and neurodegeneration, highlighting the potential for UBA1 to act as a promising therapeutic target for a range of neurodegenerative diseases." (PMID 26432019, 2015). "UBA1 represents a novel and promising therapeutic target for the treatment of neurodegenerative diseases." (PMID 26432019, 2015). "Specific links between UBA1 and neurodegenerative diseases affecting the human population have recently been established, with strong clinical and experimental data highlighting roles for UBA1 in SMA." (PMID 26432019, 2015). "The importance of UBA1 for the maintenance of neuronal health and function has triggered considerable research efforts aiming to specifically investigate the extent to which this critical ubiquitylation enzyme contributes to neurodegenerative disease." (PMID 26432019, 2015). "UBA1 contributes to the pathogenesis of several neurodegenerative diseases, including SMA and HD." (PMID 26432019, 2015). "They include those encoding eukaryotic translation initiation, elongation and translation factors, and genes that have been previously associated with other neurodegenerative diseases, like the ATP-ase family gene 3-like 2 (AFG3L2) and ubiquitin-like modifier activating enzyme 1 (UBA1)." (PMID 21915392, 2011). "Moreover, UBA1 protein expression decreases with age in mouse brains, and researchers of neurodegenerative diseases propose a threshold hypothesis where disease onset occurs once ubiquitylation capacity falls below a critical functional threshold." (PMID 39347709, 2024).